VDAC1 (voltage dependent anion channel 1)
Diseases named in the same sentence as VDAC1 in open-access papers (continued):
Sharing a sentence is not in itself a finding about the gene and the disease.
amyotrophic lateral sclerosis (17 papers, 2017 to 2025). Amyotrophic lateral sclerosis (ALS) is a neurodegenerative disease characterized by progressive muscular paralysis reflecting degeneration of motor neurons in the primary motor cortex, corticospinal tracts, brainstem and spinal cord. "Mutant SOD1 associated with amyotrophic lateral sclerosis (ALS) bound to bilayer-reconstituted VDAC1 and inhibited its channel conductance." (PMID 30542671, 2017). "Notably, cytoplasmic accumulation of TAR DNA binding protein 43 (TDP-43), a disease hallmark of amyotrophic lateral sclerosis (ALS), can trigger mtDNA release via the MPTP and VDAC1 oligomers to upregulate the NF-κB and cGAS-STING signaling." (PMID 37325622, 2023). "A second peptide, VDAC1-derived N-terminal peptide, was also developed and found to induce cancer cell death and potentially serve as a new therapeutic strategy for amyotrophic lateral sclerosis (ALS)." (PMID 36291596, 2022). "In the mouse model of amyotrophic lateral sclerosis, a misfolded mutant of superoxide dismutase 1 (SOD1) directly inhibits VDAC1 conductance, disclosing the connection of VDAC1 and SOD1 in oxidative stress." (PMID 35449127, 2022).
non-small cell lung carcinoma (16 papers, 2010 to 2025). A group of at least three distinct histological types of lung cancer, including non-small cell squamous cell carcinoma, adenocarcinoma, and large cell carcinoma. "However, the molecular mechanism underlying VDAC1 expression, especially in Non-small-cell lung cancer, remains largely unknown." (PMID 27304056, 2016). "Overexpressed MFF has been shown to interact with VDAC1 to negatively regulate VDAC1-mediated MOM permeability in non-small cell lung cancer." (PMID 35883852, 2022). "Studies have shown that VDAC1 is overexpressed in many cancer types, and VDAC1 gene expression has been identified as a predictor of poor outcomes in non-small cell lung cancer." (PMID 27659305, 2016). "Gene expression meta-analysis also identifies VDAC1 as a predictor of poor outcome in early stage non-small cell lung cancer, and silencing VDAC1 expression by siRNA has been shown to inhibit cancer cell proliferation and tumor growth." (PMID 27304056, 2016). "It was reported that higher VDAC1 expression level predicted poor outcome in non-small cell lung cancer." (PMID 24466154, 2014). "A recently published study indicated that higher VDAC1 expression level predicts poor outcome in non-small cell lung cancers." (PMID 24053408, 2013). "Overexpression of Voltage-dependent anion-selective channel protein 1 (VDAC1) predicts shorter time to recurrence and overall survival for non-small cell lung cancer." (PMID 22087286, 2011). "Here, we show using gene expression meta-analysis that VDAC1 overexpression is a strong, independent, poor prognostic factor in early stage non-small cell lung cancer based on combined analysis of multiple gene expression datasets." (PMID 21297950, 2011). "Here we show that either stable or transient knockdown of VDAC1 is sufficient to antagonize TRAIL mediated apoptosis in non-small cell lung cancer (NSCLC) cells." (PMID 20646307, 2010). "We carried out stable and transient RNAi knockdowns of VDAC1 in non-small cell lung cancer cells, and stimulated the extrinsic apoptotic pathway principally by incubating cells with the death ligand TRAIL." (PMID 20646307, 2010). "In addition, VDAC1 was found to be upregulated by microRNA-320a to promote proliferation and invasion of non-small cell lung cancer." (PMID 35729567, 2022). "In 72 non-small cell lung cancer (NSCLC) cases, overexpressed MFF formed complex with the key regulator of mitochondrial OMM permeability VDAC1 to regulate cell apoptosis." (PMID 36647167, 2023). "In A549 cells, a non-small cell lung carcinoma model representing partially differentiated alveolar epithelial type II (AT2) cells, VDAC1 depletion resulted in reprogramming to a more differentiated state, with cells resembling type I pneumocytes (AT1s) or more mature AT2 cells." (PMID 39456237, 2024). "To test this hypothesis, we conducted an in vivo gene-expression meta-analysis of surgically resected non-small cell lung cancer (NSCLC) using 602 individual expression profiles, to examine the impact of VDAC1 on survival." (PMID 21297950, 2011).
lupus (15 papers, 2020 to 2024). "For instance, alterations in VDAC1 expression or function have been associated with the pathogenesis of diseases such as lupus and multiple sclerosis." (PMID 39456237, 2024). "H3K27me3 is regulated in part by α-ketoglutarate-mediated jumonji demethylases, while VDAC1 is a mitochondrial membrane protein involved in metabolite transport and has been associated with mitochondrial cell death signaling and lupus-like autoimmunity." (PMID 33691089, 2021). "Mitochondrial dysfunction and VDAC1 overexpression are associated with various pathologies such as Alzheimer's disease (AD), type-2 diabetes (T2D), cancer, lupus, and other autoimmune diseases." (PMID 33328613, 2020). "VBIT-4 or VBIT-12 activity in preventing apoptosis and disease-associated processes was demonstrated in several disease models where VDAC1 is overexpressed, such as in type-2-diabetes (T2D), lupus, and colitis." (PMID 36077343, 2022). "VBIT-4, a VDAC1 oligomerization inhibitor, was recently shown to prevent mitochondrial dysfunction and apoptosis, as validated in mouse models of lupus and type-2 diabetes." (PMID 33328613, 2020). "As overexpressed VDAC1 triggers cell death via its oligomerization, we developed new molecules, e.g., VBIT-4 and VBIT-12, that prevent this oligomerization and subsequent apoptosis, and inhibit VDAC1 conductance, as was also validated in T2D, lupus, and colitis mouse models." (PMID 36077343, 2022). "Inhibition of the oligomerization of VDAC1 was shown to decrease lupus-like symptoms in mice." (PMID 34359907, 2021). "In this context, VDAC1 has been shown to be over expressed in cancer, in the affected regions of AD brains, in β-cells in T2D, and in autoimmune diseases such as lupus, NASH, IBD (unpublished data), and in CVDs." (PMID 33114780, 2020). "We showed that the VDAC1 oligomerization inhibitor, VBIT-4, effectively inhibits fmtDNA release, type-I interferon signaling, and disease severity in a mouse model of lupus." (PMID 39375263, 2024). "Recently, we showed that fmtDNA is released from the mitochondria via oligomeric VDAC1, and that VBIT-4 inhibits fmtDNA release, type-Ι interferon signaling, and disease severity in a mouse model of lupus." (PMID 39375263, 2024). "Using the VDAC1 oligomerisation inhibitor VBIT‐4, the authors were able to reduce lupus‐like symptoms in lupus‐prone mice, providing a rationale to target VDAC‐mediated mtDNA release in this disease." (PMID 32202065, 2020). "An interesting recent study showed that, N-terminal domain of VDAC1 interact with mtDNA and promote VDAC1 oligomerization and mtDNA release, and the VDAC oligomerization inhibitor VBIT4 decreases mtDNA release, IFN signaling and disease severity in a mouse model of systemic lupus erythematosus." (PMID 39039044, 2024). "We found that VDAC1 oligomers in the OMM promoted mtDNA release and our small molecule, VBIT-4, which inhibits VDAC1 oligomerization, decreased mtDNA release, type-Ι interferon signaling, neutrophil extracellular traps, and disease severity in a mouse model of systemic lupus erythematosus." (PMID 33114780, 2020).
prostate carcinoma (15 papers, 2015 to 2026). A carcinoma that arises from epithelial cells of the prostate gland. "VDAC1 is expressed in the mitochondria that have also been associated with the development of malignancies, including prostate cancer." (PMID 36142477, 2022). "In contrast, miR-197-3p has been shown to act as a tumor suppressor in prostate cancer by regulating the VDAC1/AKT/β-catenin Signaling Axis." (PMID 41009512, 2025). "It was reported that miR-197-3p represses VDAC1/AKT/β-catenin signaling axis to prevent prostate cancer." (PMID 39826696, 2025). "Cannabidiol induced cell death in hormone-refractory prostate cancer cells by altering mitochondrial bioenergetics through VDAC1." (PMID 39910035, 2025). "In prostate cancer, miR-197 was downregulated, and overexpression of miR-197 suppressed cell proliferation via voltage-dependent anion channel 1 (VDAC1)/AKT/β-catenin signaling." (PMID 35130798, 2022). "Induction of Cyto c release by G3139 in several melanoma and prostate cancer cell lines was found to be correlated with VDAC1 expression levels." (PMID 28824871, 2017). "In summary, our data show that embelin induces mitochondrial-dependent apoptosis by regulating the action of Bax and VDAC1 in human prostate cancer cells." (PMID 26252009, 2015). "Other examples include arbutin (hydroquinone-O-beta-d-glucopyranoside), a tyrosinase inhibitor in A375 human malignant melanoma cells, and somatostatin, used in the treatment of advanced prostate cancer, which upregulated the expression of VDAC1 and VDAC2 in the LNCaP prostate cancer cell line." (PMID 28824871, 2017).
melanoma (14 papers, 2011 to 2025). A malignant, usually aggressive tumor composed of atypical, neoplastic melanocytes. "In this study, we obtained direct evidence that VDAC1 oligomerization is essential for apoptotic mitochondrial changes, including cytochrome c release and mitochondrial membrane potential loss in melanoma cells." (PMID 26462148, 2015). "To reiterate, evaluation of the activity of OXPHOS complexes showed higher levels in BRAF-mutated and BRAF/NRAS wild-type melanoma cell lines compared to HDFs, most likely due to a higher mitochondrial mass as indicated by VDAC1 immunostaining and activity of citrate synthase." (PMID 33007949, 2020). "In addition, the aberrant melanin production because of abnormal regulation of VDAC1 may be implicated in pathological hyper- or hypo-pigmentation, such as albinism, freckles, or even life-threatening melanoma." (PMID 35649693, 2022). "In line with the present study, VDAC1 was found to be down-regulated in human esophageal carcinoma and in melanoma (cell lines UACC903)." (PMID 37046443, 2023). "It has been shown that activating transcription factor 2 (ATF2), associated with cell death or cellular stress states in several melanoma and tumor cell lines, involves Bim and VDAC1, where VDAC1 depletion significantly prevented ATF2-related apoptosis." (PMID 33114780, 2020). "Overexpression of VDAC1 was detected in tissue arrays for thyroid, lung, cervix, ovary, pancreas, melanoma, and glioblastoma cancers as well as in lung tissue samples taken from healthy and tumor-containing areas of the same patient." (PMID 28824871, 2017). "When A375 human malignant melanoma cells were treated with the tyrosinase inhibitor, arbutin, a potential anti-tumor agent, VDAC1 expression level was found to be up-regulated." (PMID 23233904, 2012). "VDAC1 knockdown inhibits apoptosis or autophagy of melanoma cells." (PMID 35649693, 2022). "VDAC1 has been shown a proapoptotic or autophagic factor in melanoma or other cancers." (PMID 35649693, 2022). "We here showed that VDAC1 knockdown promotes melanogenesis which may also contribute to the development of melanoma." (PMID 35649693, 2022). "In addition, in melanoma and prostate cancer cell lines, a positive correlation between levels of VDAC1 expression and the release of cytochrome c by G3139 was demonstrated." (PMID 27289382, 2016). "In addition, in several melanoma and prostate cancer cell lines, a correlation between levels of VDAC1 expression and induction of Cyto c release by G3139 was demonstrated." (PMID 23233904, 2012). "Therefore, continued dependence on the Bim/VDAC1 pathway may be an important contributor to BRAF inhibitor-resistant melanoma." (PMID 26462148, 2015). "In conclusion, kaempferol inhibited melanoma metastasis through stopping the aerobic glycolysis of melanoma cells, in which the binding of HK2 as well as VDAC1 on mitochondria was broken." (PMID 37239974, 2023). "Based on Western blot analysis, the expression of VDAC1 and OXPHOS complexes was generally higher in the melanoma cell lines WM3311, WM47, and A375 compared to WM3000 and HDFs." (PMID 33007949, 2020). "We again compared the samples based on VDAC1 expression and found the 6-gene signature was conserved in 8 of these cell lines, namely UACC62 and SK_MEL2 (melanoma), SF295 and SF539 (CNS), A498 and SNC12C (renal), H23 and HOP62 (NSCLC)." (PMID 21297950, 2011). "In conclusion, our work showed that VDAC1 regulates melanin production in an α-MSH/UVB–independent manner, which may provide a potential target for pigmentary disorders and melanoma." (PMID 35649693, 2022). "Several melanoma cell lines, B16F10, K1735M2, A375 and A375-R1, were treated with paclitaxel and vemurafenib to test the function of mitochondrial ATF2 and its connection to Bim and voltage-dependent anion channel 1 (VDAC1)." (PMID 26462148, 2015).
melanoma (continued). "In this study, we show that VDAC1 plays a novel role in regulating melanogenesis through the Ca2+-calcineurin-CRTC1-MITF pathway, which provides insights into understanding the regulation of melanogenesis and potential intervention target for pigmentary disorders and melanoma." (PMID 35649693, 2022).
hepatocellular carcinoma (13 papers, 2011 to 2024). A malignant tumor that arises from hepatocytes. "miR-7 also downregulates VDAC1 in hepatocellular carcinoma and influences proliferation and migration, as well as the fibroblast growth factor receptor FGFR4, a key molecule for liver protection from chronic injury." (PMID 33806891, 2021). "VDAC1 overexpressed in several cancer cell lines relative to fibroblast cell line and, in ascites hepatoma AH130 cells, the three VDAC isoforms expression levels were significantly higher than in normal liver cells." (PMID 28824871, 2017). "On the other hand, it has been reported that elements such as voltage-dependent anion channel 1 (VDAC1), which plays an important role in carcinogenesis, play prognostic roles in patients with hepatocellular cancer, and miR-7 was suggested to suppress VDAC1 expression." (PMID 36012357, 2022). "Moreover, microRNA-7 was validated to decrease the expression of VDAC1 to inhibit hepatocellular carcinoma proliferation and metastasis." (PMID 35729567, 2022). "Several studies have demonstrated that VDAC1 is remarkable expressed in malignant tumors such as uterine cervical cancer, hepatocellular carcinoma, and cholangiocellular carcinoma, indicating that it plays a significant role in high energy-demanding cancer cells." (PMID 33680287, 2021). "Other miRNAs involved in regulating VDAC1 expression include miR-320a and lncRNA-H19/miR-675, and miR-7, was reported to inhibit VDAC1 levels, cancer cell survival and metastasis in hepatocellular carcinoma, potentially by affecting the mitochondrial permeability transition pore." (PMID 39456237, 2024). "For example, miR-34a and miR-29a, which are downregulated in hepatocellular carcinoma and ovarian cancer, play a critical role in apoptosis by targeting the 3′-UTR of VDAC1 mRNA." (PMID 39456237, 2024). "For further investigation, we used 3‐BP, inhibiting HK2 bound to VDAC1, and observed that CTB contributed to the opening of mPTP and the destruction of MMP in hepatoma cells." (PMID 31994339, 2020). "Potassium ions could inhibit tumorigenesis through inducing apoptosis of hepatoma cells by upregulating potassium ions transport channel proteins HERG and VDAC1." (PMID 27069917, 2016). "Thus, our findings suggest that potassium ions could inhibit tumorigenesis through inducing apoptosis of hepatoma cells by upregulating potassium ions transport channel proteins HERG and VDAC1." (PMID 27069917, 2016).
myocardial infarction (13 papers, 2018 to 2025). Gross necrosis of the myocardium, as a result of interruption of the blood supply to the area, as in coronary thrombosis. "Circ-CBFB/miR-495-3p/VDAC1 is an innovative axis in H/R challenge cardiomyocyte injury, providing new ideas for the management of acute myocardial infarction." (PMID 36835653, 2023). "In a rat model of myocardial infarction (MI), VDAC1 is clearly increased, and inhibition of VDAC1 relieves excessive fibrosis in the atrial myocardium." (PMID 36588561, 2022). "LIP-1 can reduce the myocardial infarction size by reducing voltage-dependent anion channel 1 (VDAC1) to maintain mitochondrial structure and function." (PMID 36620630, 2022). "Immunohistochemical analysis of commercially available human cardiac tissues revealed marked overexpression of VDAC1 in post-myocardial infarction patients, as well as in patients with chronic ventricular dilatation\dysfunction." (PMID 33328613, 2020). "In agreement, rats exposed to myocardial infarction or to excessive aldosterone had a marked increase of VDAC1 in both ventricular and atrial tissues." (PMID 33328613, 2020). "Similarly, the extent of myocardial infarction was significantly greater in the MI/RI group than in the Sham group, and pAD/VDAC1 intervention promoted myocardial infarction." (PMID 40551312, 2025). "αB-crystallin seems to bind to the Voltage-Dependent Anion-selective Channel 1 (VDAC1) during hypoxic/redox stresses in neonatal mouse cardiomyocytes and to both VDAC1 and ANT during myocardial infarction." (PMID 29615920, 2018).